SLC35B4 (solute carrier family 35 member B4)
Description:
Antiporter that transports nucleotide sugars across the endoplasmic reticulum (ER) membrane in exchange for another nucleotide sugar. May couple UDP-alpha-D-glucuronate (UDP-GlcA) or UDP-alpha-D-xylose (UDP-Xyl) efflux to UDP-alpha-D-glucuronate (UDP-GlcA) influx into the ER lumen, which in turn stimulates glucuronidation and excretion of endobiotics and xenobiotics. [Isoform 1]: Has UDP-GlcA:UDP-GlcNAc antiporter activity. [Isoform 2]: Has UDP-GlcA:UDP-GlcNAc antiporter activity.
Synonyms: YEA4; FLJ14697; YEA
Tractability: Antibody: UniProt predicts a signal peptide or a membrane-spanning region.
Gene: Protein-coding gene on chromosome 7 (134,289,332 to 134,317,117, reverse strand). Ensembl gene ENSG00000205060.
Subcellular location: Endoplasmic reticulum membrane
Pathways (Reactome):
Transport of small molecules: Transport of nucleotide sugars
Gene Ontology:
Molecular function: protein binding; UDP-N-acetylglucosamine transmembrane transporter activity; UDP-xylose transmembrane transporter activity
Biological process: UDP-N-acetylglucosamine transmembrane transport; UDP-xylose transmembrane transport; transmembrane transport
Cellular component: endoplasmic reticulum; endoplasmic reticulum membrane; Golgi apparatus; Golgi membrane
Genetic constraint (gnomAD): Loss-of-function variants: 18 observed, 30.59 expected, observed/expected ratio (o/e) 0.59, 90% interval 0.41 to 0.87. The upper end of that interval is the gene's LOEUF score, 0.87, which puts it in group 3 of 6, group 1 being the genes least tolerant of losing a copy. Missense variants: 316 observed, 394.56 expected, observed/expected ratio (o/e) 0.8, 90% interval 0.73 to 0.88. Synonymous variants: 137 observed, 147.42 expected, observed/expected ratio (o/e) 0.93, 90% interval 0.81 to 1.07.
Homologues: Orthologues: chimpanzee SLC35B4 (100% identical), macaque SLC35B4 (99% identical), dog SLC35B4 (95% identical), guinea pig SLC35B4 (93% identical), rabbit SLC35B4 (92% identical), rat Slc35b4 (92% identical), mouse Slc35b4 (91% identical), pig SLC35B4 (91% identical), tropical clawed frog slc35b4 (79% identical), zebrafish slc35b4 (74% identical), Drosophila melanogaster Efr (53% identical), Drosophila melanogaster CG14511 (47% identical), and 1 more. Paralogues in human: SLC35B3 (24% identical), SLC35B1 (19% identical), SLC35B2 (15% identical).
Diseases named in the same sentence as SLC35B4 in open-access papers:
SLC35B4 is named in the same sentence as 18 diseases in open-access papers, as found by Europe PMC text mining. Sharing a sentence is not in itself a finding about the gene and the disease. The quoted sentences say what the papers report.
Obesity (4 papers, 2013 to 2019). Accumulation of substantial excess body fat. "Increased liver expression of Slc35b4, a Golgi UDP-GlcNAc antiporter, was identified as a quantitative trait locus associated with high-fat diet-induced obesity, insulin resistance and gluconeogenesis in mice." (PMID 26972830, 2016). "SLC35B4 has been identified as a potential regulator of obesity and insulin resistance in mouse models." (PMID 24455749, 2013). "SLC35B4 was cloned and firstly reported in 200535, but in the past one decade, there was almost no any report on its biological functions except few studies demonstrated that it is involved in the regulation of obesity, insulin resistance and gluconeogenesis." (PMID 31175271, 2019). "Eight genes (BCAT1, BMP2 K, CSRNP2, MYNN, NCKAP5L, SAP30BP, SLC35B4, and SP1) were isolated as candidates for obesity." (PMID 24455749, 2013).
hepatocellular carcinoma (3 papers, 2022 to 2025). A malignant tumor that arises from hepatocytes. "Most recently, it is reported that nucleotide sugar transporters, SLC35B4 contribute to c-Myc stabilization by modifying its O-GlcNAcylation in hepatocellular carcinoma." (PMID 37033243, 2023). "The roles of SLC35B4 in hepatocellular carcinoma (HCC) tumorigenesis remain unknown." (PMID 35308201, 2022).
prostate carcinoma (3 papers, 2018 to 2022). A carcinoma that arises from epithelial cells of the prostate gland. "Our experimental findings were further supported by our analysis of publicly available datasets, which showed that a high level of SLC35B4 mRNA is linked to poor prognosis in patients with prostate cancer." (PMID 29682886, 2018). "In our investigation using three different prostate cancer cohorts, we identified one SNP, rs1646724, in SLC35B4 that was consistently associated with recurrence in patients with localized disease and OS in patients with advanced prostate cancer." (PMID 29682886, 2018). "In summary, this study provides evidence for an association between the regulatory variant SLC35B4 rs1646724 and the clinical outcomes of patients with prostate cancer, which may be of prognostic or therapeutic significance." (PMID 29682886, 2018). "Further investigation revealed that rs1646724 may affect expression of SLC35B4, which encodes a glycosyltransferase, and that down‐regulation of SLC35B4 by transfecting short hairpin RNA in DU145 human prostate cancer cell suppressed proliferation, migration and invasion." (PMID 29682886, 2018). "In advanced prostate cancer, a regulatory SNP, rs1646724, influenced SLC35B4 to promote the prostate cancer proliferation, migration, and invasion." (PMID 32565801, 2020). "First, using Western blot analysis, we examined the protein level of SLC35B4 in cells from two widely used metastatic human prostate cancer cell lines, PC‐3 and DU145." (PMID 29682886, 2018). "Our results suggest that SLC35B4 warrants further investigation as a potential prognostic marker of prostate cancer." (PMID 29682886, 2018). "Future studies are warranted to validate our findings in a larger cohort and in other ethnic groups and populations, and to determine the functional importance of SLC35B4 in prostate cancer progression." (PMID 29682886, 2018). "To understand the clinical relevance of SLC35B4 expression in prostate cancer, we examined SLC35B4 expression in a large number of prostate carcinoma cases using tissue microarrays." (PMID 29682886, 2018). "Using a combination of different in vivo and in vitro assays, we demonstrated that SLC35B4 expression was increased in prostate cancer tissues and that silencing SLC35B4 expression suppressed cancer cell proliferation, migration and invasion." (PMID 29682886, 2018). "Based on these findings, we posit that SLC35B4 may alter glycosylation thereby modifying some biological processes involved in prostate cancer progression." (PMID 29682886, 2018). "As an initial step towards understanding the role of SLC35B4 in prostate cancer, we evaluated whether SLC35B4 has a role in proliferation, migration and invasion of prostate cancer cells." (PMID 29682886, 2018). "Furthermore, we found increased SLC35B4 expression correlated with more aggressive forms of prostate cancer and poor patient prognosis." (PMID 29682886, 2018).
gastric cancer (2 papers, 2019 to 2020). A primary or metastatic malignant neoplasm involving the stomach. "SLC35B4 expression was markedly higher in gastric cancer tissues and involved in the progression of gastric cancer." (PMID 32565801, 2020). "Here, using the cDNA arrays, promoter reporter assays, and chromatin immunoprecipitation assays, we demonstrated that SLC35B4 is directly transactivated by YAP1–TEADs complex in gastric cancer (GC) cells." (PMID 31175271, 2019). "By using the promoter luciferase assay and ChIP-qPCR, we first revealed that SLC35B4 is a novel downstream gene directly regulated by YAP1/TEADs in gastric carcinoma cells." (PMID 31175271, 2019). "According to this logical reasoning combined with our experiments in this study, it can help us to deeply understand the biological significance of a YAP1/SLC35B4 axis in the regulation of malignant behaviors in gastric carcinoma." (PMID 31175271, 2019). "All these results further confirmed the relationship between SLC35B4 and YAP1 in the gastric carcinoma." (PMID 31175271, 2019).
Insulin resistance (2 papers, 2013 to 2018). Increased resistance towards insulin, that is, diminished effectiveness of insulin in reducing blood glucose levels. "Genetic screening in mouse models for quantitative trait loci (QTLs) showed that the alteration of hepatic gene expression of SLC35B4 correlates in vivo with insulin resistance and gluconeogenesis." (PMID 29867058, 2018).
lung carcinoma (2 papers, 2021 to 2025). "For lung cancer, GMPS, EPHA10, C10orf54, and MAGEA6 are highly expressed in different subtypes; for liver cancer, CMYA5, DEPDC6, FAU, VPS24, RCBTB2, LOC100133469, and SLC35B4 are significantly expressed in different subtypes." (PMID 33747053, 2021).
viral infection (2 papers, 2020 to 2025). "We revealed that SLC35B4 employed its UDP-xylose transport activity to promote the HS biosynthesis pathway, thereby assisting IAV internalization into target cells in the early stage of viral infection." (PMID 40130891, 2025).
diabetes (1 paper, 2018). "SLC35B4, solute receptor for UDP-N-acetylglucosamine and UDP-xylose, is associated with diabetes and predisposing conditions." (PMID 29867058, 2018).
glioma (1 paper, 2020). A benign or malignant brain and spinal cord tumor that arises from glial cells (astrocytes, oligodendrocytes, ependymal cells). "Our data also indicated that SLC35B4 may be involved in pathogenesis of both schizophrenia and glioma, which provide hints that researchers may shed light on this glycosyltransferase gene for drug development of both two diseases." (PMID 32565801, 2020). "In the cancer side, although there was no direct study of investigating the effects of SLC35B4 on glioma, several studies suppressed SLC35B4 expression to benefit the cancer therapies." (PMID 32565801, 2020). "CAMK2D, EIF3K, MPC2, MYL12B, PAM, and SLC35B4, selected from the schizophrenia dataset and TCGA, were reevaluated in CGGA through gene expression in glioma grading and survival curves between patients having high level of gene expression and those having low level of gene expression." (PMID 32565801, 2020).
schizophrenia (1 paper, 2020). A major psychotic disorder characterized by abnormalities in the perception or expression of reality. "Recently, SLC35B4 was evaluated as an empirically significant SNP of schizophrenia through a GWAS study." (PMID 32565801, 2020).
cancer (6 papers, 2018 to 2023). A tumor composed of atypical neoplastic, often pleomorphic cells that invade other tissues. "Nevertheless, if validated, these regulatory variants or related markers in SLC35B4 may lead to better patient stratification, optimize therapeutic interventions in high‐risk patients and elucidate new cancer drug targets." (PMID 29682886, 2018). "An additional direct target of YAP/TEAD4 is a nucleotide sugar transporter, SLC35B4, which plays a key role in cancer metabolism and cancer cell proliferation." (PMID 35602596, 2022). "However, if SLC35B4 is a context-dependent target gene or a general target gene of YAP1 still needs to be further confirmed in multiple cancers in the future." (PMID 31175271, 2019). "Therefore, while it remains to be confirmed, our findings that SLC35B4 depletion could destabilize c-Myc provide an alternative approach to target c-Myc in many types of human cancer." (PMID 35308201, 2022). "In this study, we showed that the expression levels of SLC35B4 in HCC are higher than normal liver tissues, and the overexpression of SLC35B4 is correlated with the poor prognosis of cancer patients." (PMID 35308201, 2022).
tumor (3 papers, 2018 to 2022). "We find that the expression levels of SLC35B4 are higher in HCC tissues than adjacent non-tumor tissues." (PMID 35308201, 2022). "The result showed that knockdown of SLC35B4 inhibits tumor growth compared with the control group." (PMID 31175271, 2019). "In this context, the knockdown of SLC35B4 inhibits the proliferation and migration of HCC cells in vitro, and the acute depletion of SLC35B4 in HCC tumors significantly suppresses the tumor growth in vivo." (PMID 35308201, 2022). "In addition, the analysis of SLC35B4 mRNA levels in 42 paired HCC tissues and adjacent non-tumor tissues further confirmed this conclusion." (PMID 35308201, 2022).
infection (2 papers, 2023 to 2025). The state of being infected such as from the introduction of a foreign agent such as serum, vaccine, antigenic substance or organism. "We found that all five scrambled siRNA-treated mice died on days 8, 9 or 10 p.i., whereas three out of five Slc35b4 siRNA-treated mice survived the infection." (PMID 40130891, 2025).
SLC35B4 also shares sentences with these, for which no sentence is quoted: AIDS (1 paper); colorectal cancer (1); gastric tumors (1); keloid (1); liver cancer (1).